NUP37 (nucleoporin 37)
Description:
Component of the Nup107-160 subcomplex of the nuclear pore complex (NPC). The Nup107-160 subcomplex is required for the assembly of a functional NPC. The Nup107-160 subcomplex is also required for normal kinetochore microtubule attachment, mitotic progression and chromosome segregation.
Synonyms: p37; MGC5585; FLJ22618; MCPH24
Tractability: PROTAC: ubiquitination databases record sites on it; its protein half-life has been measured.
Gene: Protein-coding gene on chromosome 12 (102,073,103 to 102,120,120, reverse strand). Ensembl gene ENSG00000075188.
Subcellular location: Chromosome, centromere, kinetochore; Nucleus, nuclear pore complex
Subcellular location (Human Protein Atlas): Nucleoplasm
Pathways (Reactome):
Disease: Defective TPR may confer susceptibility towards thyroid papillary carcinoma (TPC); HCMV Early Events; HCMV Late Events; NEP/NS2 Interacts with the Cellular Export Machinery; NS1 Mediated Effects on Host Pathways; Nuclear import of Rev protein; Rev-mediated nuclear export of HIV RNA; SARS-CoV-2 activates/modulates innate and adaptive immune responses; Transport of Ribonucleoproteins into the Host Nucleus; Viral Messenger RNA Synthesis; Vpr-mediated nuclear import of PICs
Cell Cycle: Amplification of signal from unattached kinetochores via a MAD2 inhibitory signal; EML4 and NUDC in mitotic spindle formation; Mitotic Prometaphase; Nuclear Pore Complex (NPC) Disassembly; Postmitotic nuclear pore complex (NPC) reformation; Resolution of Sister Chromatid Cohesion; Separation of Sister Chromatids
Metabolism of RNA: Transport of Mature mRNA Derived from an Intronless Transcript; Transport of Mature mRNA derived from an Intron-Containing Transcript; Transport of the SLBP Dependant Mature mRNA; Transport of the SLBP independent Mature mRNA; snRNP Assembly; tRNA processing in the nucleus
Metabolism of proteins: SUMOylation of DNA damage response and repair proteins; SUMOylation of DNA replication proteins; SUMOylation of RNA binding proteins; SUMOylation of SUMOylation proteins; SUMOylation of chromatin organization proteins; SUMOylation of ubiquitinylation proteins
Metabolism: IP3 and IP4 transport between cytosol and nucleus; IP6 and IP7 transport between cytosol and nucleus; IPs transport between nucleus and cytosol; Regulation of Glucokinase by Glucokinase Regulatory Protein
Cellular responses to stimuli: Regulation of HSF1-mediated heat shock response
Immune System: ISG15 antiviral mechanism
Signal Transduction: RHO GTPases Activate Formins
Gene Ontology:
Molecular function: protein binding
Biological process: nucleocytoplasmic transport
Cellular component: kinetochore; nuclear envelope; nuclear pore outer ring; nucleoplasm; nucleus; cytosol; nuclear pore
Genetic constraint (gnomAD): Loss-of-function variants: 12 observed, 16.99 expected, observed/expected ratio (o/e) 0.71, 90% interval 0.45 to 1.14. The upper end of that interval is the gene's LOEUF score, 1.14, which puts it in group 5 of 6, group 1 being the genes least tolerant of losing a copy. Missense variants: 157 observed, 200.37 expected, observed/expected ratio (o/e) 0.78, 90% interval 0.69 to 0.89. Synonymous variants: 64 observed, 71.5 expected, observed/expected ratio (o/e) 0.9, 90% interval 0.73 to 1.1.
Homologues: Orthologues: chimpanzee NUP37 (100% identical), dog NUP37 (94% identical), pig NUP37 (94% identical), mouse Nup37 (91% identical), guinea pig NUP37 (90% identical), macaque NUP37 (88% identical), rat Nup37 (83% identical), tropical clawed frog nup37 (71% identical), zebrafish nup37 (69% identical), Drosophila melanogaster Nup37 (29% identical).
Diseases named in the same sentence as NUP37 in open-access papers:
NUP37 is named in the same sentence as 25 diseases in open-access papers, as found by Europe PMC text mining. Sharing a sentence is not in itself a finding about the gene and the disease. The quoted sentences say what the papers report.
hepatocellular carcinoma (9 papers, 2017 to 2024). A malignant tumor that arises from hepatocytes. "NUP37 overexpression in a model of hepatocellular carcinoma was associated with enhanced metastasis and invasion that decreased upon NUP37 knockdown." (PMID 31867128, 2018). "Unlike promoter/enhancer demethylation-mediated upregulation of ITPR3, MCM2 and NUP37 in hepatocellular carcinoma." (PMID 36694230, 2023). "In comparison with the expression levels in HL7702 cells, NUP37 mRNA levels were upregulated in the indicated hepatoma cell lines except for HepG2 cells." (PMID 35093119, 2022). "We also assessed the expression profiles of MCM2 and NUP37 in 5 different hepatoma cell lines and one normal liver cell line (HL7702)." (PMID 35093119, 2022). "NUP37 is a major component of the nuclear pore complex, which regulates the stability of YAP1 in a LRP5-dependent manner and promotes the progression of hepatocellular carcinoma." (PMID 38304253, 2023). "Our work comprehensively revealed that NUP37 overexpressed in both clinical HCC samples and human hepatoma cell lines." (PMID 35093119, 2022). "Our findings provide important insights into the roles of LRP5 and NUP37 in maintaining the integrity of the NPC and subsequent promotion of cancer progression in hepatocellular carcinoma (HCC)." (PMID 31881970, 2019). "One group studied the role of Nup37, a component of the NPC scaffold, in hepatocellular carcinomas (HCC)." (PMID 37894323, 2023).
breast cancer (6 papers, 2021 to 2024). A primary or metastatic malignant neoplasm involving the breast. "Basing on the database, we found that PSMG1 is highly co-expressed with NUP37 in breast cancer and also associated with poor prognosis in ER-positive patients." (PMID 34386417, 2021). "High expression of NUP37 in breast cancer patients is associated with a poorer prognosis and promotion of cell growth, migration, and stemness." (PMID 34386417, 2021). "The association between NUP37 expression and prognosis in patients with breast cancer were assessed using the Kaplan–Meier plotter online tool and OncoLnc." (PMID 34386417, 2021). "siRNAs were used to knock down NUP37 and evaluate proliferation, migration, and stemness in breast cancer cells." (PMID 34386417, 2021). "NUP37 was identified as a hub gene that is upregulated in breast cancer patients related to a significantly worse survival rate." (PMID 34386417, 2021). "Next, in order to confirm the functional effects of NUP37 on breast cancer cells, two siRNAs were applied to knockdown of NUP37 in BT-549 and ZR-75-30 cells, which are the top two cell lines with high expression levels of NUP37 in western blot assays." (PMID 34386417, 2021). "The siNUP37 exerts its inhibitory effects on the cell proliferation, migration, EMT, and cell stemness of breast cancer cells, which indicated the oncogenic role of NUP37 in the biological characteristic of breast cancer cells." (PMID 34386417, 2021). "In order to confirm the bioinformatics analysis, here, cell culture studies have been used to investigate the effects of NUP37 on the properties of breast cancer cells by siNUP37." (PMID 34386417, 2021). "The multiple bioinformatics and experimental analysis help provide a comprehensive understanding of the roles of NUP37 as a potential marker for diagnosis and prognosis and as a novel therapeutic target in breast cancer." (PMID 34386417, 2021). "Earlier studies have shown that PSMG1 is associated with increased susceptibility to inflammatory bowel disease, which can lead to diseases associated with colon cancer, whereas the co-expression relationship of NUP37 with PSMG1 was proposed to play a specific role in breast cancer." (PMID 38138918, 2023). "Furthermore, analyses of clinical human tissue specimens indicated that Nup37 protein is also highly expressed in breast cancer patients." (PMID 34386417, 2021). "As this hypothesis is a novel finding in breast cancer, it is potentially expanding the cellular functions of NUP37 and PSMG1." (PMID 34386417, 2021). "Finally, we identified PSMG1, one of the genes co-expressed with NUP37, as having a highly positive relationship with NUP37 in The Cancer Genome Atlas- Breast Cancer (TCGA-BRCA) database using Xena." (PMID 34386417, 2021). "Furthermore, we confirmed that the downregulation of NUP37 in breast cancer cells results in the inhibition of cell growth, migration, and stemness." (PMID 34386417, 2021). "Unfortunately, NUP37 knockdown was not effective in MCF7 cells or another luminal breast cancer line (T47D), preventing further interpretations about CDK4." (PMID 39333715, 2024). "Therefore, to make a stronger elucidation of the connected function of NUP37 and PSMG1 in breast cancer, future exploration would be needed." (PMID 34386417, 2021). "Since we only evaluated NUP37 as a biomarker in BRCA by publicly available database and confirmed the function of NUP37 in vitro experiments using breast cancer cell lines, an in vivo study and an outcome for breast cancer patients and NUP37 in a prospective data set are further required." (PMID 34386417, 2021). "Recent bioanalysis studies have suggested that NUP37 is a potential prognostic biomarker and oncogene for non-small cell lung cancer (NSCLC), breast cancer (BC), glioma, and pan-cancer." (PMID 39080077, 2024).
liver cancer (6 papers, 2019 to 2024). An epithelial or non-epithelial malignant neoplasm that arises from the liver. "Previous studies showed that the elevated expression of NUP37 is associated with worsened survival rates in liver cancer." (PMID 34956314, 2021). "Therefore NUP37 is regarded as a prognostic indicator for liver cancer, where high expression of NUP37 is associated with worsened patient prognosis." (PMID 31881970, 2019). "Previous studies have illustrated that the inhibition of NUP37 can significantly reduce the invasion and migration of liver cancer cells using biological inhibitors." (PMID 39174498, 2024). "Nucleoporin 37 (NUP37) is an important component of the nuclear pore complex (NPC), whose elevated expression is associated with worsened prognosis in liver cancer." (PMID 31881970, 2019). "NUP37 has been reported as an oncogene in lung and liver cancers." (PMID 35093119, 2022). "We demonstrated that knockdown of LRP5, but not LRP6 or β-catenin, markedly inhibited the proliferation of liver cancer HepG2 cells by destabilizing NUP37 and may result in the subsequent destruction of the NPC integrity." (PMID 31881970, 2019). "Indeed, similar to knockdown of LRP5, knockdown of NUP37 significantly inhibited the proliferation of HepG2 cells and Huh7 cells, as well as a non liver cancer cell line HEK-293 cells." (PMID 31881970, 2019). "Due to the fact that knockdown of NUP37 also significantly inhibited the proliferation of a separate liver cancer cell line Huh7, as well as non liver cancer cell line HEK-293, LRP5 may play a universal role in the modulation of NPC function via specific stabilization of NUP37." (PMID 31881970, 2019). "Previous studies have shown that NUP37 interacted with YAP and activated YAP/TEAD signaling in liver cancer." (PMID 31881970, 2019). "In contrast, LRP5 deficiency results in the destabilization of NUP37, and may lead to the destruction of the NPC integrity, which in turn causes dysregulation in the nuclear translocation of numerous signaling proteins, including those critically involved in the proliferation of liver cancer cells." (PMID 31881970, 2019). "Moreover, the interaction between NUP37 and low-density lipoprotein-related receptor 5 (LRP5) enhances the stabilization of NUP37, thereby facilitating liver cancer (LC) cell proliferation." (PMID 39080077, 2024).
lung carcinoma (5 papers, 2020 to 2024). "Previous studies have indicated that NUP37 fosters tumorigenesis and development by modulating the cell cycle of lung cancer cells." (PMID 39174498, 2024). "Previous studies have reported that NUP37 promotes lung cancer cell proliferation and inhibits apoptosis, while the overexpression of TGFA and HPF induces cell proliferation and invasion in lung cancer." (PMID 35963622, 2022). "As a typical feature of oncogene, it has an impact on the prognosis of cancer patients and previous reports also confirmed that the increased expression of NUP37 can significantly reduce the survival time of lung cancer patients." (PMID 34264013, 2021). "In addition, NUP37 is also concerned with the malignant progression of liver cancer, oral cancer, and non‐small cell lung cancer." (PMID 34264013, 2021).
glioma (4 papers, 2021 to 2024). A benign or malignant brain and spinal cord tumor that arises from glial cells (astrocytes, oligodendrocytes, ependymal cells). "Correlational analysis of glioma data from the TCGA database demonstrated a positive association between the expression levels of NUP37 and DNMT1." (PMID 39174498, 2024). "Although this study has identified the potential diagnostic value of NUP37 in the prognosis of glioma, the regulatory mechanism of NUP37 remains to be explored." (PMID 34264013, 2021). "Overall, the high expression of NUP37 has a certain diagnostic value for the prognosis of glioma patients." (PMID 34264013, 2021). "First, it is reported for the first time that the high expression of NUP37 as an oncogene is obviously associated with the prognosis of glioma especially grades III." (PMID 34264013, 2021). "It is the first time to explain that NUP37 as an oncogene can be used as an independent risk factor leading to poor prognosis of glioma and has clinical diagnostic value, especially in grade III glioma." (PMID 34264013, 2021). "This conclusion was further supported by multivariate analysis and meta‐analysis that high expression of NUP37 can be used as an independent risk factor to reduce the overall survival time of glioma patients." (PMID 34264013, 2021). "The results of the seven datasets as a whole showed that NUP37 was also a risk factor for glioma prognosis ([HR] = 1.98 (95% CI [1.42–2.75]))." (PMID 34264013, 2021). "A total of 7 datasets containing 1959 glioma samples were included in this analysis, and the results of the meta‐analysis found that each individual dataset revealed NUP37 as a risk factor for glioma prognosis ([HR] >1)." (PMID 34264013, 2021). "We partially revealed the mechanism of NUP37 in glioma and provided a novel potential diagnostic and therapeutic target." (PMID 34264013, 2021). "NUP37 also had better diagnostic value for the 3‐year survival of glioma patients of different grades in the three datasets." (PMID 34264013, 2021). "We partially revealed the mechanism of NUP37 in glioma and provided a potential diagnostic and therapeutic target." (PMID 34264013, 2021). "ROC curves were used to determine the diagnostic value of high NUP37 expression for glioma prognosis based on the three datasets." (PMID 34264013, 2021). "In this study, we also revealed the association between NUP37 expression and survival of glioma patients by a variety of data types to verify each other (CGGA RNA‐seq, CGGA microarray, and TCGA RNA‐seq)." (PMID 34264013, 2021). "The high expression of NUP37 in the three datasets had a better diagnostic value for the 3‐year and 5‐year survival of glioma patients (AUC >0.7)." (PMID 34264013, 2021). "The final results show that the low survival rate of glioma patients may be caused by the cell cycle and immunomodulatory function of NUP37." (PMID 35093934, 2022). "Second, through univariate analysis, we learned that NUP37 or some patient's clinical characteristics were a risk factor for glioma prognosis, but to clarify whether such a result was an independent factor, we adopted multivariate analysis to explain." (PMID 34264013, 2021). "The results of the univariate and multivariate analyses suggest that NUP37 may be used as a prognostic and diagnostic factor for glioma patients, but its diagnostic value must be further examined." (PMID 34264013, 2021). "To delve deeper into the function of NUP37 in glioma, we carried out Gene Set Enrichment Analysis (GSEA) using TCGA data." (PMID 39174498, 2024). "By using The Cancer Genome Atlas (TCGA) database, we observed that the expression of NUP37 was significantly higher in both low-grade and high-grade gliomas compared to normal brain tissues." (PMID 39174498, 2024). "In this study, we further explored the impact of NUP37 depletion on the invasion and migration of glioma cells." (PMID 39174498, 2024).